SHOC2 (SHOC2 leucine rich repeat scaffold protein)
Diseases named in the same sentence as SHOC2 in open-access papers (continued):
Sharing a sentence is not in itself a finding about the gene and the disease.
liver cancer (2 papers, 2019 to 2024). An epithelial or non-epithelial malignant neoplasm that arises from the liver. "In in-vitro culture models of liver cancer cells with gain- or loss-of-function approaches, it appears that SHOC2 regulation of growth and survival is dependent of the signal of the RAS-MAPK, but not of the mTORC1 signal." (PMID 39871893, 2024). "Finally, in this study, we made an interesting observation that SHOC2 knockdown suppressed the growth and survival of liver cancer cells in vitro, whereas Shoc2 depletion promoted liver tumorigenesis in Pten-loss model." (PMID 39871893, 2024). "However, the role of SHOC2 in the liver tumorigenesis, especially in liver cancer model induced by Pten loss remains elusive." (PMID 39871893, 2024). "However, in an in vivo liver cancer model induced by Pten-loss with mTorc activation, Shoc2 acts as a tumor suppressor, since its deletion further activates the mTorc1 signal to promote liver tumorigenesis." (PMID 39871893, 2024). "To address this, we knocked down PTEN in liver cancer cells and found it activated the mTORC1 signal as expected, but had minor, if any, effect on SHOC2 levels or the RAS-MAPK signals." (PMID 39871893, 2024). "In in vitro cell culture models, the activation of MAPK signal is more effective than the inactivation of mTORC1, thereby SHOC2 acts as an oncogene to promote the growth and survival of liver cancer cells." (PMID 39871893, 2024). "Through an analysis of the TCGA database, comprising 371 cases of liver cancer, we found that SHOC2 mRNA expression was significantly increased in liver cancer, as compared to normal liver tissue (P < 0.001)." (PMID 39871893, 2024). "On the other hand, SHOC2 knockdown significantly enhanced mTORC1 activation in amino acid or glucose-deprived liver cancer cells upon nutrition resupply, but had a minimal, if any, effect on the MAPK activation." (PMID 39871893, 2024). "In this study, we characterized the role of SHOC2 in liver cancer cells and liver tumorigenesis using both in vitro cell culture and in vivo mouse models, respectively." (PMID 39871893, 2024). "Here, we showed that SHOC2 is overexpressed in human liver cancer tissues, and SHOC2 overexpression promotes the growth and survival of liver cancer cells via activation of the RAS-MAPK signal, although the mTORC1 signal is inactivated." (PMID 39871893, 2024). "We reported here that the same observation can be extended to liver cancer cells, given the observations that ectopic SHOC2 expression activated the MAPK, but inactivated the mTORC1 signals, and vice versa upon SHOC2 knockdown." (PMID 39871893, 2024). "With regards to liver cancer, there is only one study, reporting that SHOC2 expression was increased in liver metastases of colon cancer, and SHOC2 knockdown inhibited the liver metastasis potential of HCT116 cells." (PMID 39871893, 2024). "We then used a loss-of-function approach in SHOC2 high-expressing HepG2, Hep3B, and Huh7 cells and found that SHOC2 knockdown significantly inhibited the growth of these liver cancer cell lines and clonal survival of Huh7 cells." (PMID 39871893, 2024). "SHOC2 knockdown suppresses the growth of liver cancer cells mainly through inactivating the RAS-MAPK signal." (PMID 39871893, 2024). "Whether and how SHOC2 differentially regulates the RAS-MAPK vs. the mTORC1 signals in liver cancer remains unknown." (PMID 39871893, 2024). "In this study, we used multiple in vitro liver cancer cell lines, and two in vivo liver tumorigenesis models, and concluded that SHOC2 regulates the growth and survival of liver cancer cells in vitro, and liver tumorigenesis in vivo via modulating the activity of the MAPK and mTORC1 signals." (PMID 39871893, 2024).
liver cancer (continued). "The cell line-based follow-up studies revealed that SHOC2 is required for the growth and clonogenic survival of liver cancer cells, since ectopic expression promoted, whereas siRNA-based knockdown suppressed the growth and survival, indicating that SHOC2 plays an oncogenic role." (PMID 39871893, 2024). "The fact that MAPK activation or inactivation led to growth promotion or suppression, respectively, regardless of the status of mTORC1 activation or inactivation, strongly suggested that the RAS-MAPK signal played a dominant role in SHOC2 regulation of growth and survival in liver cancer cells." (PMID 39871893, 2024). "Indeed, ectopic SHOC2 expression at the level comparable to endogenous level promoted the growth and clonal survival of both liver cancer cells." (PMID 39871893, 2024). "Interestingly, while PTEN knockdown promoted, and SHOC2 knockdown inhibited, respectively, the growth and clonal survival of liver cancer cells, the double knockdown of PTEN and SHOC2 canceled the effect of each other, showing minimal, if any, effect." (PMID 39871893, 2024). "Collectively, SHOC2 is a positive regulator of growth and survival of liver cancer cells." (PMID 39871893, 2024). "However, in the Pten loss-induced liver cancer model, Shoc2 deletion further activates mTorc1 without affecting the Ras-Mapk signal and promotes liver tumorigenesis." (PMID 39871893, 2024). "In summary, this is the first study to demonstrate that SHOC2 acts as either oncogene or tumor suppressor by regulating the MAPK and mTORC1 signals in a manner dependent of dominancy of these two signals in liver cancers." (PMID 39871893, 2024). "The results highly suggest that SHOC2 is a positive or negative regulator of the MAPK or mTORC1 signals, respectively, in liver cancer." (PMID 39871893, 2024). "In liver cancer tissues, we found that the levels of SHOC2 are positively correlated with MAPK but negatively correlated with mTORC1, further supporting the notion that SHOC2 is a positive regulator of MAPK and a negative regulator of mTORC1 in liver cancer." (PMID 39871893, 2024). "Collectively, in the in vitro cell culture models, SHOC2 mainly negatively regulates the mTORC1 signals of liver cancer cells in the absence of PTEN." (PMID 39871893, 2024). "Although we demonstrated here, for the first time, that SHOC2 acts as either an oncogene or a tumor suppressor by differentially regulating the MAPK and mTORC1 signals, using multiple liver cancer cell culture models and two liver tumorigenesis models, our study bears some limitations." (PMID 39871893, 2024). "In Pten-null liver cancer model in which the mTorc signal is activated, however, Shoc2 deletion further activates mTorc1 without affecting the Ras-Mapk signal, leading to accelerated liver tumorigenesis." (PMID 39871893, 2024). "Finally, we used the IHC staining to measure the levels of SHOC2, pERK1/2 (the MAPK signal), and pS6 (the mTORC1 signal) in liver cancer tissues and the correlations among them in a total of 150 liver tumor tissues." (PMID 39871893, 2024). "Collectively, the mTorc1 activation is the key determinant for Shoc2 action without involving the Mapk signal in this liver cancer model." (PMID 39871893, 2024). "Indeed, in this Pten-null liver cancer model, Shoc2 deletion further activated the mTORC1 signal, but not affected the MAPK signal, unlike the cell culture models, in which SHOC2 deletion significantly inactivated the MAPK signal." (PMID 39871893, 2024). "Furthermore, while double knockdown of SHOC2 and PTEN in cultured liver cancer cells did moderately affect the pERK1/2 and PTEN signals, it was much minor than what was seen in the in vivo model in which double KO of Shoc2 and Pten significantly activated the mTorc1, but without affecting pErk1/2." (PMID 39871893, 2024).
liver cancer (continued). "Here, we showed that upon SHOC2 knockdown, the MAPK activation upon serum re-supply to serum-starved liver cancer cells was attenuated, whereas the mTORC1 activation was not significantly affected." (PMID 39871893, 2024). "Thirdly, it remains to be determined why Shoc2 deletion did not change the course of liver tumorigenesis, even though the Mapk signal is remarkably inactivated in DEN-HFD liver cancer model, although it is likely and highly suggestive that the Mapk signal is not the driving force in this model." (PMID 39871893, 2024). "In this study, we used a carcinogen-induced mouse liver cancer models (DEN-HFD) to determine the role of Shoc2 in carcinogenesis and found that the pErk1/2 levels were indeed higher in tumor tissues than in adjacent normal tissues regardless of Shoc2 inactivation." (PMID 39871893, 2024).
viral infection (2 papers, 2021 to 2024). "Although the specific role of SHOC2 during virus infection is unclear, it has recently been shown to activate ERK/STAT signaling in response to bacterial flagellin in shrimp hosts, implying that SHOC2 may indeed have conserved roles in combating bacterial and viral pathogens." (PMID 38753575, 2024). "However, we show that depletion of intracellular SHOC2 or PSMC1 levels in moth or human cells promotes arbovirus replication, suggesting they have ancient roles in combating viral infection across diverse eukaryotic host species." (PMID 38753575, 2024). "Other low-TE genes include FAXDC2, STYX, and SHOC2 which are involved in the Ras/Raf/Mitogen-activated protein kinase/ERK Kinase (MEK)/Extracellular-signal-Regulated Kinase (ERK) cascade, commonly involved in viral infection, including that of coronaviruses." (PMID 34127534, 2021).
alexithymia (1 paper, 2022). An agnosia that is a deficiency in understanding, processing, or describing emotions. "Regarding psychopathology, the findings largely confirmed our hypotheses, insofar as alexithymia was significantly present in two groups, PTPN11 and SOS1, while it was credibly present in PTPN11/NSML, SHOC2, CBL, and SOS2 as well." (PMID 36012976, 2022). "For PTPN11/NSML, SHOC2, CBL, and SOS2, alexithymia was more present than expected." (PMID 36012976, 2022).
alopecia (1 paper, 2024). Hair loss usually from the scalp. "SHOC2 gene in chromosome 10q25 region upregulates the RAS-MAPK pathway and is characterized by alopecia, hyperactivity, mitral valve dysplasia, and atrial septal defect in NS." (PMID 39726952, 2024).
brain injuries (1 paper, 2022). "SHOC2 has been shown to promote neuronal autophagy and attenuate neuronal apoptosis via the miR-7670-3p/SIRT1 axis in ischemic brain injury." (PMID 35392276, 2022).
cholangiocarcinoma (1 paper, 2023). A carcinoma that arises from the intrahepatic biliary tree (intrahepatic cholangiocarcinoma) or from the junction, or adjacent to the junction, of the right and left hepatic ducts (hilar cholangiocarcinoma). "We aim to explore the roles of LncFALEC and miR-20a-5p/SHOC2 axis on the proliferation, migration, and Fluorouracil (5-FU) resistance of cholangiocarcinoma (CCA)." (PMID 37166421, 2023).
Cognitive impairment (1 paper, 2022). Abnormal cognition is characterized by deficits in thinking, reasoning, or remembering. "IQs were significantly lower in patients with variants in PTPN11, KRAS, RAF1, and SHOC2, but no specific cognitive impairments were found." (PMID 36012976, 2022).
craniosynostosis (1 paper, 2024). Craniosynostosis is defined as the premature fusion of one or more cranial sutures leading to secondary distortion of skull shape resulting in skull deformities with a variable presentation. "Craniosynostosis has been described in individuals with pathogenic variants in other genes of the RAS/MAPK pathway including BRAF, KRAS, PPP1CB, SHOC2, PTPN11, RAF1, and HRAS." (PMID 37774117, 2024).
dysplasia of the (1 paper, 2014). "The most commonly cardiac defects in patients with SHOC2 mutation are dysplasia of the mitral valve and septal defects." (PMID 24739123, 2014).
epilepsy (1 paper, 2012). A brain disorder characterized by episodes of abnormally increased neuronal discharge resulting in transient episodes of sensory or motor neurological dysfunction, or psychic dysfunction. "Patient 1 also had epilepsy and atypical neurologic signs such as chronic vocal and motor tics, never previously reported in patients with SHOC2 mutations or in any other condition due to RAS-MAPK dysregulation." (PMID 22995099, 2012).
glioblastoma (1 paper, 2025). The most malignant astrocytic tumor (WHO grade IV). "Repression of the RAF regulator SHOC2 sensitized glioblastomas to selumetinib in vitro and in vivo, suggesting a synergistic treatment strategy." (PMID 40985888, 2025). "Given its role as what we believe to be a novel therapeutic target in glioblastoma, we next validated SHOC2 as a mediator of selumetinib response." (PMID 40985888, 2025). "From a translational perspective, while no clinical compounds blocking SHOC2 exist to date, the recent structural elucidation of the SHOC2 heterotrimeric complex has facilitated potential pharmacologic strategies that may be useful in glioblastoma." (PMID 40985888, 2025). "SHOC2 perturbation to block downstream Ras outputs may thus also be useful in NF1 intact tumors as observed in other systems, and further work is needed to formally test this possibility in glioblastoma." (PMID 40985888, 2025).
lupus (1 paper, 2025). "Lupus nephritis has been documented in only one previously reported case of monogenic lupus associated with an SHOC2 alteration, and renal involvement was not a prominent feature in our patient." (PMID 40085019, 2025).
lymphoid leukemia (1 paper, 2020). A malignant lymphocytic neoplasm of B-cell or T-cell lineage involving primarily the bone marrow and the peripheral blood. "Since increased SHOC2 could provide oncogenic activation through ERK/MAPK signaling, this finding was unexpected and prompted us to investigate how SHOC2 absence would impact lymphoid leukemia cells." (PMID 32938995, 2020).
pancreatic cancer (1 paper, 2020). "Recently, it was investigated that exposure to genistein attenuates pancreatic cancer proliferation and invasion by downregulating miR-223, which targets SHOC2." (PMID 33066509, 2020). "F-Box and WD repeat domain containing 7 (FBXW7), a tumor-suppressive E3 ligase, is known to degrade SHOC2 leucine-rich repeat scaffold protein (SHOC2), which activates Ras/ERK signaling in pancreatic cancer." (PMID 33066509, 2020).
psoriasis (1 paper, 2024). An autoimmune condition characterized by red, well-delineated plaques with silvery scales that are usually on the extensor surfaces and scalp. "The figure shows that after accounting for known up- and down-regulation expression patterns in psoriasis, only at the endpoint TNFAIP3, SHOC2 and HTR2A expression is retained." (PMID 39337694, 2024).
tics disorders (1 paper, 2012). "Thus, one could speculate that in our patient dysregulation of RAS-MAPK due to dysregulated SHOC2 function might be related to tics disorders through an alteration of dopamine-signaling." (PMID 22995099, 2012).
cancer (20 papers, 2014 to 2026). A tumor composed of atypical neoplastic, often pleomorphic cells that invade other tissues. "This shows that fitness defects caused by SHOC2 inactivation in cancer cell lines are directly associated with the oncogenic activity of H/K/NRAS and are independent of MRAS." (PMID 35768504, 2022). "Dependency on SHOC2 was particularly evident in cancer cell lines with certain H/K/NRAS hotspot mutations (G13/Q61), indicating that SHOC2–PP1C complex formation with these mutated RAS isoforms is a likely driver of cell growth." (PMID 35768504, 2022). "Multiple KRAS-mutant cancers were recently shown to be vulnerable to the loss of SHOC2 in the context of MEK inhibition, confirming the link between SHOC2 and MAP kinase pathway-driven cancers." (PMID 33554860, 2021). "Furthermore, many gain- and loss-of-function approaches found that loss-of-function of SHOC2 was related to impaired cell motility and delays cell attachment, while gain-of-function of SHOC2 was associated with oncogenic ERK signaling in cancer." (PMID 35392276, 2022). "In line with these oncogenic roles of SHOC2 in human cancers, we recently showed that Shoc2 deletion in the KrasG12D pancreatic tumor model significantly inhibited pancreas growth and progression of murine pancreatic intraepithelial neoplasms (mPanINs)." (PMID 39871893, 2024). "SHOC2 has shown synthetic lethality in KRAS-mutant cancer lines, such as in MiaPaca2 cells treated with MEK inhibitors, which, after initial pathway inhibition, cause pathway rebound and increased RAS GTP loading." (PMID 35830882, 2022). "SHOC2 mediates tumourigenesis and metastasis in different cancer types via tethering RAS and CRAF proteins in close proximity and thus promoting RAS-mediated CRAF activation." (PMID 34103645, 2021). "This study highlights a critical role for SHOC2 as part of the MRAS-SHOC2-PP1 phosphatase complex for oncogenic ERK signalling in NSCLC, the leading cause of cancer-related mortality." (PMID 31182717, 2019). "However, most prior investigations have primarily focused on the canonical role of SHOC2 in regulation of the RAS-MAPK signal, particularly in cancer cells carrying K-Ras, N-Ras, and B-Raf oncogenic mutations or in KrasG12D-induced mice tumor models." (PMID 39871893, 2024). "A majority of SHOC2 studies in defining its role in cancer used human cancer cell lines, and only two studies involved the use of genetically modified mouse models, one for lung tumorigenesis, and the other for pancreatic tumorigenesis, both driven by oncogenic Kras mutant (KrasG12D)." (PMID 39871893, 2024). "Moreover, elevated SHOC2 and PSMC1 expression has been associated with poorer clinical outcomes among cancer patients." (PMID 38753575, 2024). "Furthermore, previous in vitro studies have revealed a strong correlation between SHOC2 expression and the proliferation of cancer cells." (PMID 39871893, 2024). "For instance, RAF1 and SHOC2, which encode CRAF and SHOC2 respectively, have been shown to be important in KRAS-mutant cell lines, suggesting inhibition of CRAF and SHOC2 could be used in KRAS-mutant cancer." (PMID 37669923, 2023). "Interestingly, we found significant co-dependencies of SHOC2 and canonical RAS proteins in cancer cells expressing oncogenic RAS with GTP-activating mutations but no co-dependency to MRAS in this setting." (PMID 35830882, 2022). "Our analysis of the DepMap data shows that MRAS knockout is well tolerated in cancer cell lines that are strongly dependent on SHOC2 for survival, consistent with the hypothesis that H/K/NRAS may substitute for MRAS in certain contexts." (PMID 35768504, 2022). "Therefore, dual targeting of SHOC2 and MEK appears as a promising treatment strategy in RAS-mutated cancers." (PMID 34103645, 2021).